IL10 (interleukin 10)
Diseases named in the same sentence as IL10 in open-access papers (continued):
Sharing a sentence is not in itself a finding about the gene and the disease.
asthma (518 papers, 2004 to 2026). "A recent study found that it had asthma protection operating through IL-6-mediated epigenetic activation of IL-10 production and with associated effects on the intestinal microbiome." (PMID 40401951, 2025). "The inverse regulation of IL‐10 levels observed in our study further confirmed that pyroptosis was effectively inhibited and asthma‐associated lung injury was protected upon KIF1B silencing." (PMID 41384344, 2025). "The asthma exacerbation group was found to have elevated levels of MDSC that were associated with increased levels of IL-10, an anti-inflammatory cytokine." (PMID 40083432, 2025). "Th9 cells, through secretion of cytokines such as IL-9, IL-10, and IL-21, are implicated in amplifying Th2-associated lung inflammation, with IL-9 considered a particularly important mediator of asthma pathology." (PMID 41515904, 2025). "Reduced IL-10 expression during viral infection in the early life is associated with asthma development by 6 years of age, indicating an important role of IL-10 in asthma development." (PMID 39902293, 2024). "IL-10 is relevant in both asthma (associated with eosinophils) and COPD (associated with neutrophils), indicating a possible impaired resolution of inflammation in these conditions." (PMID 38774212, 2024). "Conversely, c-aAb targeting the anti-inflammatory cytokine IL-10 were associated with faster clinical stability in women, and GM-CSF-specific c-aAb were found to be associated with asthma and bronchiectasis in men." (PMID 39606243, 2024). "Multiple investigations have been undertaken in different populations to investigate the association between IL10 rs1800896 polymorphism and asthma in children." (PMID 37937689, 2023). "The association between IL10 rs1800896 polymorphisms and pediatric asthma risk was evaluated using a meta‐analysis." (PMID 37937689, 2023). "Several studies have explored the potential association between IL10 rs1800896 polymorphism and the risk of asthma in children, but the findings have been inconsistent." (PMID 37937689, 2023). "Interleukin-10 is linked to the prevention of asthma due to its immunosuppressive and anti-inflammatory properties." (PMID 37760982, 2023). "Knock-down of lncRNA CRNDE reduced the lung injury caused by the asthma induction, increased the IL-10 content, and decreased the contents of IL-17A and IL-6 considerably while reducing the number of Th17 cells in the spleen." (PMID 36743692, 2023). "In a study evaluating the plasma of patients with asthma, IL-10 and IL-13 were elevated, associating both with an important role in inflammation." (PMID 37834157, 2023). "Studies have shown that there is a relationship between IL-10 levels and the severity of allergic disease and asthma, with lower levels of IL-10 associated with more severe disease." (PMID 37760982, 2023). "Secretion of IL6 and IL10 by differentiated macrophages has been described in immunosuppressive tumor-associated -macrophages, rheumatoid arthritis, asthma and regulating epithelial integrity in the small intestine." (PMID 36561744, 2022). "Numerous published studies found an association between polymorphisms, chiefly located in the promoter region of IL10, and asthma or COPD." (PMID 35456412, 2022). "On the other hand, IL-10 plays an important role in reducing airway inflammation in OVA-induced asthma as IL-10 deficient mice display greater peribronchiolar inflammation consisting of lymphocytes, macrophages and eosinophils." (PMID 35273509, 2022). "In the current study, we also noted that RES caused significant induction of IL-10 which is produced by the regulatory T cells (Tregs) that play a crucial role in controlling asthma." (PMID 35265071, 2022). "In contrast, our findings show that the Imuno TF upregulated the Foxp3 expression associated to increase of IL-10 secretion in lung of asthma animals, indicating that Imuno TF also upregulates Treg cells response." (PMID 36685604, 2022).
asthma (continued). "Overall, autophagy is increased in key effector cells in asthma and this is linked to increased T2 inflammation and suppression of the anti-inflammatory cytokine IL-10." (PMID 35608088, 2022). "Patients with comorbidities, such as diabetes, asthma, and hypertension, are at higher risk of mortality because of the excessive production of inflammatory cytokines, including IL-2R, IL-10, and TNF." (PMID 34046036, 2021). "Children carrying the C allele for TaqI were more likely to develop asthma, and interleukin-10 levels were significantly low in asthmatics with the TC genotype for TaqI due to a decrease in expression of VDR." (PMID 33633666, 2021). "MDSCs are a primary source of IL-10, therefore studying the association between MDSC/IL-10 levels in asthma is important." (PMID 32931721, 2020). "The presence of the C allele is associated with high levels of IL-10; there are studies that have showed decreased levels of IL-10 in serum and sputum in asthma patients in comparison with healthy subjects." (PMID 31936183, 2020). "Accordingly, asthma induction also significantly decreased Treg-associated IL-10 and TGF-β production while significantly increasing Th2-associated IL-4, IL-5, and IL-13 production and Th17-associated IL-17 production (p < 0.05)." (PMID 33072079, 2020). "With regards to childhood asthma, this SNP seems to lead decreased LPS-induced IL-12(p70) and IL-10 responses and further increase the risk for asthma, especially atopic asthma." (PMID 32650475, 2020). "IL-10 is a cytokine with pleiotropic effects, considered as one of the main regulatory cytokines and extensively associated with asthma and allergy diseases." (PMID 31143187, 2019). "The absence, or reduced concentration of IL-10, associated with asthma enables the continued secretion of pro-inflammatory cytokines that contribute to lower airway inflammation, including IL-6, IL-5, IL-4, TNF-α, and IL-1." (PMID 31694631, 2019). "The combination of higher CG methylation levels of LMO2_E148, IL10_P325 and GSTM1_P266 corresponded to the highest risk of asthma." (PMID 31214241, 2019). "Our study also shows that prenatal PTS exposure is associated with higher CG methylation levels of LMO2 or IL10, and the combination of higher LMO2_E148, IL10_P325 and GSTM1_P266 methylation levels presented the highest risk of childhood asthma, 43.48%." (PMID 31214241, 2019). "To further expand our understanding of glucocorticoid action, we used cells from healthy individuals who respond to dexamethasone by increases in IL-10 and IL-17A but are devoid of any confounding asthma-associated defects." (PMID 30598515, 2019). "The concentration of Treg cells, as well as FoxP3 expression and IL-10 production are deficient in asthma thereby contributing to airway inflammation and disease activity." (PMID 30967873, 2019). "Taken together, these data suggest that asthma-induced susceptibility is partially due to the inhibition by IL-10 of immune effector mechanisms controlling Brucella multiplication in the lungs." (PMID 30147700, 2018). "When analyzed using multivariate linear regression with the covariates of asthma status, age, BMI, and sex, IL10 cytokine expression was positively associated with IL10 methylation (p = 0.030)." (PMID 29317916, 2018). "Polymorphisms in the gene of IL-10 has been defined to play a substantial role in the inflammatory response during the onset of asthma." (PMID 30915130, 2018). "Polymorphisms in the IL-10 gene have been associated with some immune-related diseases such as asthma, systemic lupus erythematosus, Crohn's disease, rheumatoid arthritis, tuberculosis, type 2 diabetes, and several types of cancer." (PMID 30186038, 2018). "While excessive production of cytokines in lung tissue is sufficient to explain most pathogenic features of asthma, expression level of many cytokines such as IL-10 and IL-17A in blood cells needs to be investigated." (PMID 30915130, 2018).
asthma (continued). "Functional impairments or defects in CD9+ IL-10-secreting regulatory B cells are associated with enhanced asthma-like inflammation and airway hyperresponsiveness." (PMID 30622536, 2018). "Asthma was significantly associated with higher differentially methylated regions (DMRs) of the Foxp3 promoter region (p = 0.030) and the IL10 intronic region (p = 0.026)." (PMID 29317916, 2018). "Further, several studies have shown that polymorphisms in the IL-10 promoter are associated with asthma, possibly due to decreased IL-10 production." (PMID 28552993, 2017). "Th9 cells, a new type of CD4+T lymphocytes, mainly secrete interleukin (IL)-9 and IL-10, which are closely linked with asthma." (PMID 27518187, 2016). "A genetic study reinforce the opposite relation between IgE and IL-10, showing that polymorphisms in IL-10 promoter were associated with high total serum IgE and increased risk for asthma." (PMID 27454771, 2016). "Stronger IL-10 and Treg responses are present in people with cagA+ strains, perhaps explaining the stronger protective associations between asthma and CagA+ infections." (PMID 28943607, 2015). "In the current analysis, higher IL‐10 or IFN‐γ was only associated with asthma in the context of high IL‐5 and IL‐13 productions; children who produced IL‐10 but no IL‐5 (Class 1), or IFN‐γ but no IL‐5 (Class 2) were not at increased risk of asthma." (PMID 26061524, 2015). "Earlier studies on this cohort of 166 infants hospitalised for bronchiolitis at less than six months of age reported that SNPs in the IL-10 gene were associated with severe rhinovirus bronchiolitis and post-bronchiolitis asthma." (PMID 26473365, 2015). "A recent meta-analysis suggested that IL-10 promoter polymorphisms were associated with asthma risk." (PMID 25759826, 2014). "Individuals with the Asp299Gly TLR4 polymorphism were shown to have decreased IL-12 and IL-10 levels produced by mononuclear cells stimulated with LPS and a four-fold higher risk of asthma." (PMID 24524443, 2014). "Stratification by ethnicity indicated an association between the IL-10 -1082 G allele and asthma in East Asian (OR = 0.74, 95% CI = 0.57–0.96, p = 0.02)." (PMID 23335974, 2013). "Since cytokine production is genetically controlled at the transcription level, the association of IL-10 polymorphisms at the genotypic or haplotypic levels with asthma has been reported in a numerous studies." (PMID 23335974, 2013). "Inhaled corticosteroids have a protective effect on severe asthma exacerbations and inhibit the synthesis of Th2 cytokines, which are implicated in asthma pathogenesis, and induce IL-10, a potent anti-inflammatory cytokine in airway epithelial cells." (PMID 23896653, 2013). "Analysis using the recessive, dominant model, and homozygote contrast showed the same pattern for the IL-10 -1082 G allele, showing an association between IL-10 -1082 G/A polymorphism and asthma." (PMID 23335974, 2013). "A meta-analysis was conducted on IL-10 -1082 G/A, -819 C/T, -592 C/A polymorphisms, and their haplotypes and asthma." (PMID 23335974, 2013). "Six publications (1372 asthmatic subjects and 1266 control subjects) reported on the genotype frequency of IL-10 -592 C/A polymorphism and asthma." (PMID 23335974, 2013). "Further, IL-10 and the IL-10 promoter region contain polymorphisms that are associated with asthma susceptibility, though this is disputed in other studies, and serum IL-10 concentrations are lower in children with atopic asthma compared to normal children." (PMID 23327606, 2013). "Various studies from different populations have been carried out to assess the association between IL-10 polymorphisms and asthma, either at the genotypic or the haplotypic level." (PMID 23335974, 2013). "In conclusion, this meta-analysis demonstrates that IL-10 -1082 G/A polymorphism confers susceptibility to asthma in East Asians and adult asthmatics." (PMID 23335974, 2013).
asthma (continued). "Deviation from H-W equilibrium among controls implies potential bias during control selection, or genotyping errors, but excluding these studies did affect our result for an association between the IL-10 -1082 G/A polymorphism and asthma." (PMID 23335974, 2013). "SNPs associated with lower IL-10 mRNA expression are also overrepresented in patients with RA, severe asthma, and SLE." (PMID 23755052, 2013). "Meta-analysis of association between the IL-10 promoter haplotype (−1082 G/A, −819 C/T, −592 C/A) and asthma." (PMID 23335974, 2013). "In the present study, we addressed associations between the IL-10 -1082 G/A, -819 C/T, -592 C/A polymorphisms, and their haplotypes and asthma susceptibility." (PMID 23335974, 2013). "Seven case-control studies (1802 asthmatic subjects and 1709 control subjects) were included on the relationship between IL-10 promoter haplotype and the susceptibility of asthma." (PMID 23335974, 2013). "Stratification by ethnicity indicated an association between the IL-10 -1082 G allele and asthma in East Asians (OR = 0.74, 95% CI = 0.57–0.96, p = 0.02), but not in West Asians." (PMID 23335974, 2013). "The IL-10 -1082 G/A polymorphism conferred susceptibility to asthma in East Asians and adult asthmatics." (PMID 23335974, 2013). "The involvement of IL-10 in the prevention of asthma and of IL-10 mutations in the onset of asthma is already well established in humans and mice." (PMID 23091602, 2012). "Based on these findings, it is likely that the mechanisms underlying the regulation of inflammatory responses in asthma by S. mansoni antigens involve IL-10, T-regulatory cells, and other mechanisms such as the expression of CTLA-4." (PMID 22934153, 2012). "It was shown that T cells from children with asthma produce less IL-10 mRNA, and severe asthma in adult is associated with reduced frequency of IL-10 producing CD4+ T cells." (PMID 21197090, 2010). "In contrast, SNPs located in the 3' end of the IL10 gene (rs3024498 and rs3024492) were associated with asthma in the replicate samples." (PMID 19852851, 2009). "Arginase-1 in macrophages is induced by Th2 type cytokines such as IL-4, IL-10, IL-13 and IL-21 and increased arginase is associated with resistance to worm infections, allergic conditions such as asthma and Th2 induced pathologies." (PMID 19696894, 2009). "A number of SNPs in the IL10 gene surrounding the promoter region and extending up to intron 1 were significantly associated with asthma in the SLSJ collection." (PMID 19852851, 2009). "Accordingly, it makes biological sense that a low IL10-producing haplotype would be associated with asthma, which is consistent with most of the literature." (PMID 19852851, 2009). "Second, our results are in line with well established associations of SNPs in IL4(-589C>T) and IL10 with asthma and atopy." (PMID 16759385, 2006). "Another study found that 12,13-DiHOME altered the expression of PPARγ-regulated genes in human dendritic cells while also reducing the secretion of the anti-inflammatory cytokine IL-10 and the number of Treg cells in the intestines of neonates at high risk of allergy or asthma." (PMID 39858271, 2025). "The exact mechanism of IL-10 in human asthma remains unclear, but a decrease in IL-10 expression has been closely linked to the exacerbation of asthma in clinical patients, as well as increased eosinophils and circulating IgE levels." (PMID 41312367, 2025). "This unexpected finding suggests that there may be an increased research interest in the association between IL10 rs1800896 polymorphisms and pediatric asthma in these regions." (PMID 37937689, 2023). "However, studies exploring the association between the IL10 rs1800896 polymorphism and asthma in children have yielded conflicting outcomes, contributing to the inconsistency in the current understanding." (PMID 37937689, 2023). "One cytokine commonly associated with asthma is interleukin‐10 (IL‐10)." (PMID 37937689, 2023).
asthma (continued). "In conclusion, IL10 rs1800896 polymorphism may be useful as a predictive marker for childhood asthma in Asians, although further studies are needed to validate the study results." (PMID 37937689, 2023). "In addition, severe steroid-resistant asthma is associated with failure of IL-10 enhancement by patient cells in response to dexamethasone." (PMID 38093354, 2023). "Studies in animals suggest the Foxp3+ pTregs and IL-10-producing Tr1 cells may contribute to the differences of asthma susceptibility associated with different genetic background." (PMID 35757774, 2022). "They demonstrated that in asthma, the Th1 cytokines and IL-10, which are produced to a lesser degree, were associated with protection from exacerbation, whereas Th2 cytokines, which on the other side are increased, were associated with increased disease severity." (PMID 36362795, 2022). "This study shows that neutrophilic asthma with low FEV1 is associated with high numbers of IRF5+, and low numbers of IL10+ macrophages, which may be the result of combined effects of smoking and having asthma." (PMID 35387061, 2021). "Authors found a decrease of interleukin 10 in those children which might increase the risk for allergic diseases and asthma later in life." (PMID 33902677, 2021). "This issue is particularly relevant now that it is known that pleiotropic IL-10 is subjected to multiple polymorphisms that may determine a predisposition for several chronic diseases such as asthma, rheumatoid arthritis or inflammatory bowel disease." (PMID 34829906, 2021). "In conclusion, our study has shown that neutrophilic asthma with low FEV1 is associated with high numbers of IRF5+, and low numbers of IL10+ macrophages, which may be the result of the combined effects of smoking and having asthma." (PMID 35387061, 2021). "In addition, a second cohort of 103 infants with LRTI identified low-IL-10-producing SNPs in association with obstructive parameters using impulse oscillometry, resembling patients with asthma-like symptoms at age six." (PMID 32357557, 2020). "The IL10 gene codes for the IL-10 protein, this gene is highly polymorphic, and many SNPs in this gene have been associated with allergic disease, wheezing in children, and childhood asthma phenotypes." (PMID 31936183, 2020). "Studies have shown that IL-10 induced in chronic schistosomiasis suppresses atopy in African children, and infection with Schistosoma mansoni has been associated with a reduced course of asthma." (PMID 31886302, 2019). "Furthermore, polymorphisms in the IL10 gene resulting in low IL-10 production have been associated with severe asthma." (PMID 31396220, 2019). "In this study, we sought to identify some CpG sites in specific genes that could be associated with asthma regulation (Foxp3 and IL10) and to identify the different AAPs for which exposure prior to the blood draw is linked to methylation levels at these sites." (PMID 29317916, 2018). "Similarly, we found that asthma was significantly associated with normalized methylation at all three CpG sites in region 3 of intron 4 of IL10 (p < 0.05)." (PMID 29317916, 2018). "While IL-10 deficiency in BALB/c mice strongly reduces asthma-induced susceptibility (158- to 1.7-fold increase for HDM and 1,148- to 75-fold increase for Alt), this is not the case of IL-12p40 deficiency (158- to 1,324-fold increase for HDM and 1,148- to 74,131-fold increase for Alt)." (PMID 30147700, 2018). "Previous study showed that Belamcandae and Ephedrine Decoction can improve the immune function of the patients (effectively preventing hypersensitivity), improve clinical effects in the treatment of pediatric cough-variant asthma, and modify IL-10 and IL-13 serum levels." (PMID 27378824, 2016). "Asthma was associated with reductions in RSV‐induced IL‐10 and RV‐induced CXCL8 responses." (PMID 27042305, 2016).